BCL2L1 (BCL2 like 1)
Diseases named in the same sentence as BCL2L1 in open-access papers (continued):
Sharing a sentence is not in itself a finding about the gene and the disease.
cancer (continued). "An analysis of published RNAseq datasets from previous reports revealed that BCL2L1 levels were elevated in TI-Tregs across many cancer types and species in comparison to Tregs from normal tissues and other TI-T cell types." (PMID 33627663, 2021). "BCL2L1 (Bcl-xL) was found to be a driver in colorectal tumorigenesis and cancer progression, which is in agreement with its protumour effect in the FRGS." (PMID 34717544, 2021). "Alternative splicing has been demonstrated to have a key role in cancer development, and data indicate that alternative splicing of key genes such as BCL2L1, RON and FOX2 can drive a cancer phenotype." (PMID 32437477, 2020). "BCL2L1 is known to have roles in apoptosis and has been proposed as a drug target for cancer treatment." (PMID 32034170, 2020). "The regulation of BCL2L1 alternative splicing is of critical importance to the apoptotic process and is highly relevant to cancer." (PMID 33163396, 2020). "Here, we found that the extract of Cotyledon orbiculata, a South African medicinal plant, had an anti-proliferative effect in cancer cells, mediated by apoptosis induced by alternative splicing of hnRNPA2B1 and BCL2L1." (PMID 33163396, 2020). "Copy number variations have been detected in the anti‐apoptotic members MCL1 and BCL2L1 across 26 human cancers, including gynaecologic cancers." (PMID 32419250, 2020). "Further experimental observations are needed to confirm antiapoptotic or proapoptotic roles by targeting BCL2L1-HRAS in human cancer." (PMID 32101536, 2020). "Suppression of the anti-apoptotic proteins MCL1, BCL2, and BCL2L1 by BH3 mimetics has been well-known to induce the BAX/BAK-modulated mitochondrial death pathway of pro-apoptotic proteins in cancer cells." (PMID 32486166, 2020). "The SF3B1 inhibitor E7107 in combination with Bcl-xL/Bcl-2 inhibitors enhances cytotoxicity to cancer cells based on the evidence that E7107 alters splicing of MCL1, but not that of BCL2L1." (PMID 33064779, 2020). "Aripiprazole was able to modulate the gene expression of certain pro- (Caspases 3, and BCL10, and anti-apoptotic genes (BCL2L1, and c-myc) those play an important role in regulating the apoptosis, and hence progression of cancer." (PMID 32746451, 2020). "Treatment of HCT116, OE33, and KYSE70 cancer cells with varying concentrations of C. orbiculata extract results in modulation of splicing of both hnRNPA2B1 and BCL2L1." (PMID 33163396, 2020). "The alternative spliced BCL2L1 can modulate cell apoptosis to escape from cell death in cancer, which is critical for tumorigenesis." (PMID 31133010, 2019). "Although BCL-2 protein was investigated in various of cancers apoptosis studies, BCL-xL, a protein encoded by gene BCL2L1, is considered as a more effective marker than BCL-2." (PMID 28877725, 2017). "The fact that of the 10 rarely mutated genes, 5 (BCL2L1, CDC42, DDX5, AKT1 and APC) are listed in cancer gene databases indicates such association-based selection is useful." (PMID 27808240, 2016). "Although it has been recognized that anti-apoptotic members of BCL-2 family (e.g., BCL2L1/BCL−xL), inhibit autophagy and apoptosis of cancer cells, little known is about the biological function of pro-apoptotic members (e.g., BCL2L11/Bim, BID)." (PMID 26517093, 2015). "In this study, we set out to first identify cancer types that show high levels of BCL2L1 amplification using genomic mining." (PMID 26134786, 2015). "The ZNF217 gene belongs to the 20q13 region, a region frequently amplified in human cancers and importantly, ZNF217 protein interferes and cooperates with proteins encoded by other genes present in this region (AURKA, BCL2L1, eEF1A2)." (PMID 26431164, 2015).
cancer (continued). "Genes that are commonly modulated as a result of OPNc overexpression in both OvCar-3 and PC-3 cells (Bcl2l1, Bad, Fos, Itgav, Itgb3, Vegfa and Serpine1) are presumably required for shared functions related to cancer progression in both tumor models." (PMID 24928374, 2014). "Overexpression of BCL2L1 suppresses mitochondrial-mediated apoptosis and enhances cancer cell survival in cancer models." (PMID 22355333, 2012). "Recently, the let-7 family as well as miR-886-5p were shown to regulate apoptosis of cancer cells by targeting BCL2L1 and BAX, respectively." (PMID 21629653, 2011). "For example, volasertib can cause downregulated BCL2L1 expression, disrupt the interaction between PLK1 and NEK7, or displacement of HMGB2 from mitotic chromosomes, thereby affecting mitotic arrest and apoptosis in cancer cells." (PMID 39872221, 2025). "They showed that BCL2L1 inhibition combined with radiotherapy reduces tumour growth more effectively than radiotherapy alone and propose BCL2L1 inhibition as a potential combination anti-cancer therapy." (PMID 40650785, 2025). "The result suggested that BCL2L1 was a key downstream molecule of the pro-cancer effect of CLU." (PMID 40606578, 2025). "Overall, our multidimensional, integrated genomic approach identified MCL1 as a promising therapeutic target in several BCL2L1-methylated pediatric cancers, offering a translational strategy to identify patients most likely to benefit from MCL1 inhibitor therapy." (PMID 39846250, 2025). "In addition, the DepMap database confirms that BCL2L1 is one of the major genes that modulates MCL1 dependency in cancer cell lines." (PMID 41438049, 2025). "Indeed, BCL2L1 expression was shown to prevent apoptosis, thereby conferring multi-drug resistance to cancer cell lines." (PMID 38797968, 2024). "Moreover, by analyzing BCL2L1 in matched microarray datasets composed of 303 cell lines and RNA-seq datasets composed of 294 cell lines, the researchers found cancer cells with low BCL2L1 (BCL-XL) expression were more sensitive to SY-1365." (PMID 38566153, 2024). "This cluster is enriched in the Hippo signaling pathway (KEGG:04390) (Bonferroni-corrected p-value = 1.56e−3), WNT Signaling Pathway (KEGG:04310) (Bonferroni-corrected p-value = 9.57e−3) and Pathways in cancer (KEGG:05200) with genes such as BCL2L1, MYC, FOS (Bonferroni-corrected p-value = 0.047)." (PMID 38057321, 2023). "It is intriguing that the apoptosis inhibitor BCL2 is among the target genes of YAP1, a fact that could contribute to YAP1 dependency in 20q11.21 amplified cancers, given that the related BCL2L1 protein is dysregulated in these cancers." (PMID 34577783, 2021). "Furthermore, OV patients in stage II, III, or IV shared similar gene expression patterns for SPTBN2 or BCL2L1 in cancer tissues." (PMID 34179092, 2021). "Additionally, RBM4 can also antagonize the oncogenic SR protein SRSF1 to regulate BCL2L1 splicing and inhibit cancer cell growth." (PMID 33803452, 2021). "We observed that SRSF10 plays a crucial role in HNC tumorigenesis by affecting the pro-death, pro-survical splice variants of BCL2L1 (BCL2 Like 1: BCLx: Apoptosis Regulator) and the two splice variants of PKM (Pyruvate kinase M), PKM1 normal isoform to PKM2 cancer-specific isoform." (PMID 34616729, 2021). "Cancer-associated genes of the locus include ASXL1, DNMT3B, BCL2L1, TPX2, KIF3B and POFUT1." (PMID 34577783, 2021). "BCL2L1 is one of the most common amplified genes among cancers." (PMID 34351305, 2021). "Furthermore, genetic and pharmacologic targeting of MCL1 or BCL2L1 has been shown to effectively improve the sensitivity of cancer cells to radiotherapy." (PMID 32404045, 2020). "Finally, while the expression of the cell death inducer MDM2 was decreased in cancer EVs-exposed cells, the expression of the anti-apoptotic factor BCL2L1 was increased." (PMID 31200749, 2019).
cancer (continued). "In consistence to this, our data indicates DMAP1 pY246 facilitates transcription of antiapoptotic-gene BCL2L1 under mitotic arrest in cancer cells, which is linked to its negative effects on Bub3 pS211-mediated DNA methylation at BCL2L1promoter." (PMID 30553276, 2018). "In cancer cells, the synergistic effect induced by enhanced E2F and mTOR activities changed the gene expression of some components in cell proliferation/survival signaling, such as Bcl2l1 and insulin-like growth factor 1 receptor (Igf1r)." (PMID 28076433, 2017). "ERK1/2 and AKT are known to modulate anti-apoptotic signaling in cancer, and shRNA-mediated knockdown of MERTK in ALL cell lines decreased expression of genes encoding pro-survival proteins BCL2L1 (BCL-XL), PIK3R5 (phosphotidylinositol 3 kinase—PI3K), and PRKCB (protein kinase C—PKC)." (PMID 27834816, 2016). "Above all, we can hypothesize that copy‐number variations (CNVs) in BCL2L1 and MCL1 may be associated with cancer prognosis." (PMID 27264345, 2016). "Since cancer types with BCL2 and MCL1 amplification are more prone to inhibition of these proteins, we reasoned that significant frequency of BCL2L1 amplification in a particular cancer type may indicate dependency on BCL-XL for survival." (PMID 26134786, 2015). "The results suggested that mtTFA is a prognostic factor for a poor outcome of human cancer and may function as an antiapoptotic factor, regulating target genes, such as BCL2L1 and survivin." (PMID 26307971, 2015). "BCL2L1 was found to play a functional role in colon, prostate, and pancreatic cancers." (PMID 25333947, 2014). "Therefore, the splicing control of BCL2L1 may play a central role in regulating the apoptotic process and therapeutic response in cancers." (PMID 39254643, 2024). "miRNA targeted gene pathway interaction identified BCL7A, BCL2L1, LIN28A, KLF6, GATA6, solute carrier family genes and ZNF genes associated with erythropoiesis, cell cycle regulation, glycosphingolipid biosynthesis, cAMP, cGMP-PKG, mTOR, MAPK and PI3K-AKT signaling pathways and cancer pathways." (PMID 36295630, 2022). "Furthermore, metastasis‐associated cellular features including proliferation, survival and cancer stem cells (CSCs) of CRC cells were greatly dependent on transcription of SE‐associated oncogenes (e.g., BCL2L1, CCDC137), which were exceptionally vulnerable to SE interruption by CDK12 inhibition." (PMID 36254394, 2022). "Notably, BCL2L1-gained cancer was even resistant to BCL-2-targeted agents." (PMID 34351305, 2021). "Previous studies showed that MALAT-1 promotes cancer progression, mainly through the regulation of gene expression, for example, the epithelial mesenchymal transition associated genes, ZEB1, ZEB2, and Slug and the apoptosis related genes, CASP3, CASP8, BAX, BCL2, and BCL2L1." (PMID 26989678, 2016). "Because cancer types with BCL2 and MCL1 amplification are more prone to inhibition of their respectively encoded proteins, we hypothesized that cancers with a significant frequency of BCL2L1 amplification would have greater dependency on BCL-XL for survival." (PMID 26134786, 2015). "Increased expression of BCL2 family members including MCL1, BCL2L1 (BCL-xL), BCL2A1 (BFL1), and BCL2 itself drives resistance to single-agent venetoclax in various cancers." (PMID 39894894, 2025). "However, as methylation of DNA is considered a stable change in DNA that is less susceptible to treatment-induced alterations compared with gene expression, BCL2L1 methylation at cg00300298 may be a better predictor of MCL1 inhibitor response in pediatric cancer." (PMID 39846250, 2025). "We also investigated the dependency profile of BCL2 family proteins (BCL2, BCL2L10, BCL2A1, BCL2L1, and MCL1) in GBM within Cancer Cell Line Encyclopedia, and found that GBM cells show the greatest dependency on Bcl-xL (BCL2L1) for survival." (PMID 38383492, 2024).
cancer (continued). "BCL2L1, an antiapoptotic factor highly expressed in P4 hESCs, has been shown to be a downstream target of YAP1 in cancer cell models." (PMID 36596852, 2023). "Specifically, it induces cancer cell apoptosis by modulating BCL2L1 splicing and shifting to the pro-apoptotic Bcl-xS isoform." (PMID 33803452, 2021). "All three genes from this locus that are listed as cancer-related at OncoKB knowledgebase (ASXL1, DNMT3B, BCL2L1) are amplified in the 12 cell lines." (PMID 34577783, 2021). "Because STAT3 regulates genes that promote cancer cell survival, proliferation, and invasion, we next tested mRNA expression changes of previously established STAT3 target genes, BCL2L1, BIRC5, CCND1, and MMP9 after short-term Olaparib exposure." (PMID 34956861, 2021). "Surprisingly, BCL2L1, E2F1, HRAS, MAPK8, MITF, RELA, and SP1 were all found in the mitophagy and cancer pathways." (PMID 34262589, 2021). "The observed cytostatic effects are in agreement with previous studies showing that STAT3 can protect cancer cells from the apoptotic effects of many individual drugs: STAT3 activity controls the expression of pro-survival genes such as MCL1, BCL2 and BCL2L1." (PMID 32231398, 2020). "Gossypol directly interacts with and inhibits anti-apoptotic factors, BCL-2 and BCL-2-like protein 1 (BCL2L1, also named BCL-XL), enacting apoptotic cell death in cancer." (PMID 33066509, 2020). "We next sought to explore the underlying mechanisms of the synergistic effect of combining BCLxL (encoded by BCL2L1) inhibition with splicing modulator E7107, which may assist to shed light on the mechanism-based therapeutic strategies of splicing modulators in cancer treatment." (PMID 30635584, 2019). "Four target genes (BCL2L1, IGF1R, MAPK8, and FAS) and 5 signaling pathways (PI3K-Akt, FoxO, MAPK, pathways in cancer, and proteoglycans in cancer) were identified." (PMID 30497474, 2018). "BLC2 (which was downregulated) and BCL2L1 are anti-apoptotic; IL8 and CXCL2 are chemokines that are pro-inflammatory and enhance the proliferation and survival of cancer cells." (PMID 29188362, 2018). "CCND1 (FC 2.59), BCL2L1 (FC 2.25), MYC (FC 3.70), along with CCND2 (FC 1.60) and SOCS7 (FC 1.51), are all located downstream of STAT activation and were upregulated in carcinoma tissue." (PMID 30603058, 2018). "NF-κB serves as a critical link between inflammation and cancer through its ability to upregulate the expression of tumor-promoting cytokines, such as IL6 and TNFA, and survival genes, such as BCL2L1 (BCLXL)." (PMID 27713747, 2016). "Network 14 and 15 show networks with AKT, and APP, BCL2L1, IGM as a central node, which show cancer, haematological disease, and immunological disease, respectively." (PMID 27463006, 2016). "Numerous genes located on 20q have been reported to have altered expression as a consequence 20q gain, including several well-known cancer-related genes, such as AURKA (20q13.2), BCL2L1 (20q11.21) and AIB1 (20q12)." (PMID 23577133, 2013). "For example, the apoptotic regulator BCL2L1, adjacent to TPX2, has been previously suggested as a 20q11 amplification target in cancer." (PMID 21103391, 2010). "Gene expression analysis suggests that its mechanism of action may involve downregulation of cancer-related genes such as AKT1, BCL2L1, CCND1, CDK4, PLK1, and RHOA." (PMID 38751791, 2024).
cancer (continued). "Our findings that both BCL2L1 and MAPK1 are co‐expressed in key biological pathways related to drug resistance, apoptosis and PIK3‐AKT signaling are in agreement with other studies in both NSCLC and other cancer types." (PMID 39718015, 2024). "In addition to ESCs, YAP1 activation in cancer cells increases survival through the induction of BIRC5 and BCL2L1, both of which are important for hESC survival." (PMID 36596852, 2023). "In addition to CCND1, several other cancer-relevant genes, including MCL1, BCL2L1, CDC25, FAS, and HIF1A, were among the common genes." (PMID 36807142, 2023). "Moreover, focal CNA amplifications encompassed genomic peaks that harbored canonical cancer genes including those found at HPV-integrated hotspots (MYC, MYCN, MYCL, SOX2, NR4A2, and ANKRD12), and others (CCNE1, SMAD2, BCL2L1, and GNAS)." (PMID 36216793, 2022). "We further compared the relative expression of these molecules in 14 cancer types containing paired tumor and normal samples and found that approximately half of the autophagy regulators showed elevated expression in different cancers, including BIRC5, RIPK2, MET, ITGA6, BCL2L1, CASP4, etc.." (PMID 36261830, 2022). "BCL2L1 inhibits caspase-1 activation by interfering with NLRP1 oligomerization, a key component of the inflammasome immune response, and ITP3 has an anti-apoptotic effect in mammalians cancer cells." (PMID 33676414, 2021). "These CAFs do not alter proliferation rate of cancer cells but markedly upregulate the expression of the anti-apoptotic BCL2L1 gene in folicular lymphoma cells." (PMID 34503172, 2021). "Notably, BCL2L1, E2F1, HRAS, MAPK8, MITF, RELA, and SP1 were found in both mitophagy and cancer pathways." (PMID 34262589, 2021). "Since each long and short isoform of Mcl-1 and Bcl-X have anti- apoptotic/pro-apoptotic function in cancer cells, A2780 and HCT116 cells were used to determine whether T3 altered splicing to the apoptosis-related MCL1 and BCL2L1 genes." (PMID 33064779, 2020). "Gene expression analysis revealed that its mechanism of action might be attributed, in part, to downregulation of cancer-related genes, such as AKT1, BCL2L1, CCND1, CDK4, PLK1, and RHOA." (PMID 31527550, 2019). "MEK targeted cancer therapies were previously shown to induce YAP activity as a survival mechanism, where nuclear active YAP promotes tumorigenesis by inducing expression of the anti-apoptotic protein BCL-xL (BCL2L1)." (PMID 30717152, 2019). "BCL2L1 and MCL1 are key anti‐apoptotic genes, and critical for cancer progression." (PMID 27264345, 2016). "Those pathways specifically altered in primary tumors were associated with an abnormally increased expression of genes that are involved in focal adhesion (e.g., PRKCA, CRK, and BCL2), PI3K-Akt signaling (e.g., PHLPP2, PRKCA, PPP2R3A and KIT) and cancer pathways (e.g., COL4A5, LAMC1 and BCL2L1)." (PMID 27662660, 2016). "Additionally, BAG3 interacts with the anti-apoptotic BCL-2 protein family members (BCL2, Bcl-XL/BCL2L1, and MCL1) leading to their enhanced stability and inhibition of apoptosis in cancer cells." (PMID 24467529, 2014). "Moreover, mutations of FBWX7, ERBB2, TET2, BCL2L1, NOTCH1, FGFR1 and TSC1 were only detected in patients without germline cancer-associated variants." (PMID 30850667, 2019). "Interestingly, all four target genes were covered, or at least partially covered, by the five signaling pathways identified: BCL2L1 and IGF1R are involved in PI3K-Akt signaling, IGF1R and MAPK8 in FoxO signaling, IGF1R and FAS in proteoglycans in cancer, and MAPK8 and FAS in MAPK signaling." (PMID 30497474, 2018). "To test this hypothesis using cancer cell lines identified in the present study to be less sensitive to fadraciclib, we determined the effects of fadraciclib combined with BCL2 inhibitor venetoclax (ABT-199), or BCL2/BCL2L1/BCL2L2 (bcl-w) inhibitors ABT-263 or ABT-737 in THP-1." (PMID 32645016, 2020).